CEP72 (centrosomal protein 72)
Description:
Involved in the recruitment of key centrosomal proteins to the centrosome. Provides centrosomal microtubule-nucleation activity on the gamma-tubulin ring complexes (gamma-TuRCs) and has critical roles in forming a focused bipolar spindle, which is needed for proper tension generation between sister chromatids. Required for localization of KIZ, AKAP9 and gamma-tubulin ring complexes (gamma-TuRCs). Involved in centriole duplication. Required for CDK5RAP22, CEP152, WDR62 and CEP63 centrosomal localization and promotes the centrosomal localization of CDK2.
Synonyms: KIAA1519; FLJ10565
Tractability: PROTAC: ubiquitination databases record sites on it.
Safety:
Unwanted effects reported when the protein is acted on. In parentheses: how it was acted on, where the effect was seen, and who reports it.
peripheral nervous system diseases (source: ClinPGx)
Gene: Protein-coding gene on chromosome 5 (612,330 to 667,168, forward strand). Ensembl gene ENSG00000112877.
Subcellular location: Cytoplasm, cytoskeleton, microtubule organizing center, centrosome; Cytoplasm, cytoskeleton, microtubule organizing center, centrosome, centriolar satellite
Subcellular location (Human Protein Atlas): Centriolar satellite; Centrosome; Basal body
Pathways (Reactome):
Cell Cycle: AURKA Activation by TPX2; Loss of Nlp from mitotic centrosomes; Loss of proteins required for interphase microtubule organization from the centrosome; Recruitment of NuMA to mitotic centrosomes; Recruitment of mitotic centrosome proteins and complexes; Regulation of PLK1 Activity at G2/M Transition
Organelle biogenesis and maintenance: Anchoring of the basal body to the plasma membrane
Gene Ontology:
Molecular function: protein binding; identical protein binding
Biological process: centriole replication; gamma-tubulin complex localization; regulation of protein localization to centrosome; spindle organization
Cellular component: centriolar satellite; centrosome; cytosol
Genetic constraint (gnomAD): Loss-of-function variants: 72 observed, 62.19 expected, observed/expected ratio (o/e) 1.16, 90% interval 0.96 to 1.41. The upper end of that interval is the gene's LOEUF score, 1.41, which puts it in group 5 of 6, group 1 being the genes least tolerant of losing a copy. Missense variants: 875 observed, 821.92 expected, observed/expected ratio (o/e) 1.06, 90% interval 1.01 to 1.13. Synonymous variants: 352 observed, 352.26 expected, observed/expected ratio (o/e) 1, 90% interval 0.92 to 1.09.
Homologues: Orthologues: chimpanzee CEP72 (92% identical), macaque CEP72 (76% identical), mouse Cep72 (67% identical), rat Cep72 (67% identical), guinea pig CEP72 (65% identical), dog CEP72 (63% identical), rabbit CEP72 (58% identical), zebrafish cep72 (23% identical). Paralogues in human: LRRC36 (26% identical).
Diseases named in the same sentence as CEP72 in open-access papers:
CEP72 is named in the same sentence as 27 diseases in open-access papers, as found by Europe PMC text mining. Sharing a sentence is not in itself a finding about the gene and the disease. The quoted sentences say what the papers report.
neuropathy (5 papers, 2015 to 2026). A disorder affecting the nervous system that manifests with pain, tingling, numbness, and/or muscle weakness. "In a recent GWAS of vincristine-induced peripheral neuropathy in pediatric acute lymphoblastic leukemia patients, a promoter SNP of CEP72 was genome-wide significantly associated with neuropathy risk." (PMID 25689802, 2015). "Emerging evidence also links additional genetic variants to toxicities associated with other key agents used in ALL treatment regimens, including variants in SLCO1B1 associated with methotrexate-related gastrointestinal toxicity and variants in CEP72 associated with vincristine-induced neuropathy." (PMID 42239520, 2026). "CEP72 rs924607 is associated with neuropathies, and ADME analyses show associations between neuropathies and ABCC1 rs3784867, and SLC5A7 rs1013940." (PMID 34948113, 2021). "Analysis of the continuation phase (following induction) studies showed significantly higher odds for neuropathy in CEP72 rs924607 TT homozygotes (odds ratio: 2.28; p = 0.02; 95% CI: 1.16–6.87)." (PMID 32802391, 2020).
Barrett's oesophagus (3 papers, 2016 to 2022). "The CEP72 region has also been implicated in a genome-wide meta-analysis of Barrett’s oesophagus and oesophageal adenocarcinoma, for which hiatus hernia is a major risk factor." (PMID 36584111, 2022). "The CEP72 protein is associated with several cancers: it is upregulated in osteosarcoma, and a meta-analysis study identified a risk locus for Barrett’s esophagus and esophageal adenocarcinoma near the CEP72 gene." (PMID 30149579, 2018).
leukemia (3 papers, 2019 to 2021). A malignant (clonal) hematologic disorder, involving hematopoietic stem cells and characterized by the presence of primitive or atypical myeloid or lymphoid cells in the bone marrow and the blood. "SNP variant rs924607 T allele in the CEP72 promoter can create a transcription suppressor binding site, thereby reducing the expression of CEP72 in human neurons and leukemia cells, and increasing their sensitivity to VCR." (PMID 34955843, 2021). "Furthermore, the CEP72 promoter single nucleotide polymorphism rs924607 genotype T was shown to create a binding site for a transcriptional repressor thus reducing CEP72 expression in human neurons and leukemia cells and increasing their sensitivity to VCR." (PMID 32802391, 2020). "The same study employed shRNA impairment of the CEP72 mRNA expression in in vitro model systems and confirmed findings that reduced CEP72 expression in induced pluripotent stem neuronal cells as well as in leukemia cells increases their sensitivity to VCR." (PMID 30832275, 2019).
acute lymphoblastic leukemia (2 papers, 2015 to 2020). Leukemia with an acute onset, characterized by the presence of lymphoblasts in the bone marrow and the peripheral blood. "We analyzed the findings of four previous studies to find out if a variant of a gene important for in cell division called centrosomal protein 72 is associated with more neurological toxicity in children treated with vincristine for acute lymphoblastic leukemia." (PMID 32802391, 2020). "We examined the utility of the rs924607 TT genotype of the centrosomal protein 72 (CEP72) as a potential biomarker for predilection toward vincristine-induced peripheral neuropathy in children treated for acute lymphoblastic leukemia." (PMID 32802391, 2020).
lung adenocarcinoma (2 papers, 2015 to 2025). A carcinoma that arises from the lung and is characterized by the presence of malignant glandular epithelial cells. "The genes CEP72, BRD9, TRIP13, SLC9A3, SDHA, SLC6A19 and PDCD6 did not have any predictive role in lung adenocarcinoma prognosis." (PMID 26497366, 2015).
ciliopathies (1 paper, 2020). "Co-immunoprecipitation experiments demonstrated that CCDC66 interacts with numerous proteins that function in ciliogenesis (i.e. CEP72, CEP290 and PCM1) and CEP290 has also been previously implicated in retinal degeneration in human ciliopathies and mouse models." (PMID 33273526, 2020).
glioma (1 paper, 2023). A benign or malignant brain and spinal cord tumor that arises from glial cells (astrocytes, oligodendrocytes, ependymal cells). "Overall, the expression of LIN9, MCM8, CEP72, POLA1, DBF4, NDE1 and CDKN2C increase the prognostic risk for patients with glioma." (PMID 37349788, 2023). "The correlation between E2F4 and LIN9, MCM8, CEP72, POLA1, DBF4, NDE1 or CDKN2C expression in glioma tissues was analyzed using CGGA." (PMID 37349788, 2023).
Hepatic fibrosis (1 paper, 2026). The presence of excessive fibrous connective tissue in the liver. "CEP72 deficiency accelerates the progression of liver fibrosis through the EGR1-TNF-α signaling pathway." (PMID 42087233, 2026). "Notably, CEP72 deficiency markedly exacerbated liver fibrosis, as evidenced by significantly increased granuloma size and enhanced collagen deposition in both S. japonicum-infected and CCl4-treated mice." (PMID 42087233, 2026). "This study identifies a previously unrecognized protective role of CEP72 in hepatic fibrosis and highlights its potential as a novel therapeutic target for the treatment of S. japonicum-induced and other types of inflammation-associated liver fibrosis." (PMID 42087233, 2026). "Centrosomal protein 72 (CEP72), a key regulator involved in maintaining cellular architecture and integrity, is significantly upregulated during the progression of hepatic fibrosis; however, its specific biological function in this pathological process remains largely elusive." (PMID 42087233, 2026).
Hernia (1 paper, 2022). "Evidence for shared susceptibility was further provided at nine loci including 2p21 (THADA), 3p14.3 (ERC2), 3p13 FOXP1, 4q34.1 (HAND-AS1), 5p15.33 (CEP72), 7p15.2 (LOC646588), 7q33 (CALD1) and 9q22.31 (BARX1) of which eight were previously discovered on individual hernia GWAS analyses." (PMID 36584111, 2022).
Primary microcephaly (1 paper, 2019). Head circumference below 2 standard deviations below the mean for age and gender at birth. "Furthermore,neurodevelopmental disorders such as primary microcephaly are associated withmutations in proteins that interact with the centrosomes, such as the CEP72, which was considered an H-B in our analysis." (PMID 30985858, 2019).
cancer (8 papers, 2012 to 2024). A tumor composed of atypical neoplastic, often pleomorphic cells that invade other tissues. "Therefore, this study aimed to investigate the influence of SNPs in ABC family transporter genes (ABCB1 rs1128503, ABCC1 rs246240, and ABCC2 rs717620) and the CEP72 gene (rs924607) on the risk of VIPN in a Caucasian pediatric population diagnosed with cancer." (PMID 39201483, 2024). "This may be a reason that knockdown Cep72 could cause abnormalities in the cancer cell lines." (PMID 36277211, 2022). "All in all, consistent with our experiments in cancer cells, lymphoblastoid cells derived from patients with WSS also showed diminished recruitment of Cep72 and its associated proteins involved in MT nucleation." (PMID 39661677, 2024). "A retrospective cohort study was conducted to investigate the potential association of drug transporter genes from the ATP-binding cassette (ABC) family and the centrosomal protein 72 (CEP72) gene with the development of PN in 88 Caucasian children diagnosed with cancer and treated with VCR." (PMID 39201483, 2024). "Many proteins belong to these families are closely related to cancers, which means ‘CEP72’, ‘CEP131’ and ‘GPR83’ might be predicted as being TC-associated in the future." (PMID 32164526, 2020). "However, additional genes linked to cancer processes were found deregulated in this study including AHRR, C7, CLPTM1L, and MRPS30 involved in apoptosis, CDH6 in cell adhesion and CEP72 in the cell cycle." (PMID 22412903, 2012).
peripheral neuropathy (5 papers, 2015 to 2024). A disorder affecting the peripheral nervous system. "An overview of genes other than CEP72 that have been reported as potential biomarkers for vincristine-induced peripheral neuropathy." (PMID 32802391, 2020). "A recent GWAS of docetaxel-induced peripheral neuropathy identified a gene implicated in neurodegeneration (VAC14), and a gene related to cellular structure (CEP72) was identified in a GWAS for vincristine-induced neurotoxicity." (PMID 30909387, 2019).
CEP72 also shares sentences with these, for which no sentence is quoted: oesophageal adenocarcinoma (3 papers); COVID-19 (2); lymphoma (2); B-cell lymphoma (1); chronic kidney disease (1); colon cancer (1); colorectal cancer (1); cystic fibrosis (1); Hiatus hernia (1); multiple sclerosis (1); neurodevelopmental disorder (1); non-Hodgkin lymphoma (1); osteosarcoma (1); retinal degeneration (1); tumor (1).